RIOK2 (RIO kinase 2)
Diseases named in the same sentence as RIOK2 in open-access papers (continued):
Sharing a sentence is not in itself a finding about the gene and the disease.
leukemia (2 papers, 2024). A malignant (clonal) hematologic disorder, involving hematopoietic stem cells and characterized by the presence of primitive or atypical myeloid or lymphoid cells in the bone marrow and the blood. "Deletion of RIOK2 leads to reduced protein synthesis and ribosomal instability, leading to apoptosis in leukemia cells." (PMID 38307903, 2024). "RIOK2 depletion leads to ribosome instability, decreased protein synthesis in leukemia cells, and apoptosis." (PMID 38699234, 2024).
non-small cell lung carcinoma (2 papers, 2019 to 2022). A group of at least three distinct histological types of lung cancer, including non-small cell squamous cell carcinoma, adenocarcinoma, and large cell carcinoma. "RIOK2 is highly expressed in a variety of cancers, including non-small-cell lung cancer where high RIOK2 expression was correlated with poor outcome." (PMID 30991936, 2019).
adrenocortical carcinoma (1 paper, 2022). "Interestingly, positive correlations between RIOK2 mRNA and nodal metastatic status were established in six different cancer types, namely adrenocortical carcinoma, breast invasive carcinoma (BRCA), KICH, COAD, KIRC, and THCA (p < 0.05)." (PMID 36518977, 2022).
anemia (1 paper, 2024). A reduction in the number of red blood cells, the amount of hemoglobin, and/or the volume of packed red blood cells. "Haploinsufficiency of Riok2 leads to decreased erythroid precursor frequency causing anemia, and several studies have highlighted a role of RIOK2 in various cancer types." (PMID 38564577, 2024).
bladder urothelial carcinoma (1 paper, 2022). "Overexpression of RIOK2 in bladder urothelial carcinoma (BLCA), ESCA, HNSC, KIRP, LIHC, and THCA was strongly associated with poor patient outcomes." (PMID 36518977, 2022).
breast carcinoma (1 paper, 2022). "RIOK2 protein levels were significantly elevated in breast cancer, lung adenocarcinoma (LUAD), UCEC, and KIRC, which was in concordance with the high levels of RIOK2 mRNA in KIRC and LUAD (Student’s t-test, p < 0.05)." (PMID 36518977, 2022).
lymph node metastasis (1 paper, 2022). "The overexpression of RIOK2 in non-small cell lung cancer (NSCLC) was associated with poor clinical outcomes, clinical stage, differentiation, and lymph node metastasis." (PMID 36661680, 2022).
oral cancer (1 paper, 2022). "As expected, RIOK2 knockdown led to a significant decrease in protein synthesis of oral cancer cell lines." (PMID 36661680, 2022). "RIOK2 knockdown strongly reduced the colony formation capacity of oral cancer cell lines, suggesting that RIOK2 expression is essential for cell growth in oral cancer cell lines." (PMID 36661680, 2022). "Our data also suggest that RIOK2 expression contributes to oral cancer cell growth, ribosome biogenesis, and protein synthesis." (PMID 36661680, 2022). "S6 protein is one of the compartments of the 40S ribosomal subunit in eukaryote cells, which suggests that RIOK2 knockdown affects ribosomal biogenesis in oral cancer cell lines." (PMID 36661680, 2022). "To examine the effect of RIOK2 expression on cell growth, we chose HSC-2 and KOSC-2 oral cancer cell lines that possessed the highest endogenous RIOK2 expression." (PMID 36661680, 2022). "Further examination to completely clarify the molecular mechanisms and function of RIOK2 expression in oral cancer is therefore needed." (PMID 36661680, 2022). "The precise mechanisms by which RIOK2 expression mediates cell growth and protein synthesis in oral cancer remain unknown." (PMID 36661680, 2022). "The present study showed the effect of RIOK2 expression on S6 ribosomal protein expression and protein synthesis in oral cancer cell lines, suggesting that RIOK2 inhibition can induce ribosomal stress in oral cancer cell lines." (PMID 36661680, 2022). "Consistent with these previous studies, we showed that RIOK2 expression was significantly correlated with a worse outcome in TSCC patients and that a decrease in RIOK2 expression affected cell growth in oral cancer cell lines." (PMID 36661680, 2022).
Oral Squamous Cell Carcinoma (1 paper, 2022). "Inhibition of RIOK2 expression by siRNA decreased cell growth and S6 ribosomal protein expression in oral squamous cell carcinoma cell lines." (PMID 36661680, 2022).
cancer (8 papers, 2013 to 2024). A tumor composed of atypical neoplastic, often pleomorphic cells that invade other tissues. "The results show that RIO kinase 2 is highly expressed in all types of cancer and is significantly associated with tumor survival, metastasis, and immune cell infiltration." (PMID 36518977, 2022). "To identify the involvement of RIOK2 in cancer systematically, we integrated multi-omics data of 33 cancer types to conduct the first comprehensive association analyses of RIOK2." (PMID 36518977, 2022). "We found that the infiltration levels of CD8+T cells, CD4+Th2 cells, CD4+Treg cells, and cancer-associated fibroblasts increased with elevated RIOK2 expression." (PMID 36518977, 2022). "Kaplan–Meier analysis showed that RIOK2 expression in cancer cells was significantly associated with poor prognosis in TSCC patients (log-rank p = 0.013)." (PMID 36661680, 2022). "In this study, for the first time, we found that elevated RIOK2 expression, methylation, mutation and hyper-phosphorylation were surprisingly common across multiple cancer types." (PMID 36518977, 2022). "This is the first and most comprehensive analysis of the cancer-associated disruption of RIOK2." (PMID 36518977, 2022). "Cancer types with high RIOK2 mutation levels included UCEC, SKCM, BLCA, and CHOL." (PMID 36518977, 2022). "Finally, we probed for associations between RIOK2 mutations and overall survival, disease-specific survival, disease-free survival, and progression-free survival for all cancers." (PMID 36518977, 2022). "Further studies are required to investigate if there is a therapeutic window allowing for the safe and efficient targeting of RIOK2 in cancer." (PMID 38564577, 2024). "The role of RIO kinases in cancer has been increasingly investigated, with the RIOK2 ATPase activity essential for cell survival." (PMID 38699234, 2024). "With mixed reports of its behavior, we sought to understand the potential mechanism of RIOK2 activity in pan-cancer using functional gene and protein interaction networks." (PMID 36518977, 2022). "Based on our novel conceptualization of RIOK2-mediated tumorigenesis and development, we performed a pan-cancer analysis based on multi-omics for a comprehensive panel of RIOK2 for the first time." (PMID 36518977, 2022). "By describing the function of RIOK2 in pan-cancer, we demonstrate that RIOK2 represents a valuable target for treating malignant tumors." (PMID 36518977, 2022). "Our results revealed that RIOK2 is involved in the regulation of immune checkpoint expression in pan-cancer." (PMID 36518977, 2022). "We identified that RIOK2 was highly expressed in pan-cancer and was significantly correlated with tumor cell proliferation, migration, invasion, and immune cell infiltration, all of which can prove fatal to patients." (PMID 36518977, 2022). "We performed Cox proportional hazards regression to further confirm the impact of RIOK2 target gene expression on patient survival across the pan-cancer cohort." (PMID 36518977, 2022). "Here, we conducted an integrated pan-cancer analysis comprising 33 cancer-types to determine the function of RIO kinase 2 in malignancies." (PMID 36518977, 2022). "The results indicated that elevated RIOK2 expression was common in most cancer patients, with our values ranging from 0.699 to 0.975." (PMID 36518977, 2022). "In conclusion, this study is the first comprehensive analysis of multi-omic features of RIOK2 across pan-cancer and helps in unraveling the role of RIOK2 in cancer." (PMID 36518977, 2022). "First, we performed differential gene expression analysis to assess the relationship between RIOK2 expression, nodal metastasis status, and pathological stages in pan-cancer." (PMID 36518977, 2022). "To investigate the protein expression levels of RIOK2 in pan-cancer, we obtained proteomic expression data for seven cancer types and normal pairs from the CPTAC database." (PMID 36518977, 2022).
cancer (continued). "The expression of five proteins in Cluster2 that were related to RIOK2 was assessed using purity-adjusted partial Spearman’s rho-value as the degree of their correlation in pan-cancer, as illustrated in our radar chart." (PMID 36518977, 2022). "To better understand the relationship between RIOK2 and tumor-immune escape, we profiled and compared the changes in RIOK2 expression and tumor microenvironment immune cell composition in pan-cancer." (PMID 36518977, 2022). "Previous studies showed that NSC139021 binds to RIOK2 and inhibits levels of ERG and RIOK2 protein in the context of ERG-positive cancer cells." (PMID 34572430, 2021). "Considering that a variety of cell types are present in tumors, we applied partial Spearman’s correlation to determine whether RIOK2 was expressed by cancer cells." (PMID 36518977, 2022). "Therefore, over-phosphorylation of RIOK2 in tumors suggests its potential functional importance in pan-cancers." (PMID 36518977, 2022). "We observed that pan-cancer tumors had distinct DNA methylation profiles and that a negative correlation existed between DNA methylation levels in the promoter region of RIOK2 and RIOK2 expression levels." (PMID 36518977, 2022). "The results demonstrated that high expression of RIOK2 was associated with CD8+T cells, CD4+Th2 cells, CD4+Treg cells, and cancer-associated fibroblast infiltration in pan-cancer, whereas CD4+Th1 cells, macrophages, and natural killer cells showed the opposite association." (PMID 36518977, 2022). "In previous investigations, RIOK2 mRNA expression in metastases was higher in SKCM compared to the primary focus, which may indicate that RIOK2 expression is related to cancer metastasis (Wilcoxon p-value < 0.05)." (PMID 36518977, 2022). "After further functional validation, RIOK2 may be utilized as a cancer biomarker which can be utilized to implement novel targeted therapies for a range of tumors." (PMID 36518977, 2022). "Of note, although evidence concerning the association between gene alterations and cancer is mounting, no clinical data existed for the correlation between RIOK2 alterations and tumors." (PMID 36518977, 2022). "A range of new and powerful bioinformatics tools revealed that RIOK2 is a candidate target across many cancer types which may stimulate novel ideas and strategies for the development of anti-neoplastic drugs." (PMID 36518977, 2022). "Moreover, RIOK2 inhibition has been shown to decrease cell proliferation and induce cell-cycle arrest and apoptosis in cancer." (PMID 36661680, 2022). "Although several reports have demonstrated the consequences of RIOK2 inhibition in cancer progression, it remains unclear whether RIOK2 expression contributes to ribosomal function and progression in TSCC." (PMID 36661680, 2022). "Given the high expression of RIOK2 in pan-cancer, we investigated whether RIOK2 was required for tumor progression to worsen prognosis and shorten patient survival." (PMID 36518977, 2022). "There is growing evidence that RIOK2 is a potential target for cancer treatment." (PMID 36661680, 2022). "In this study, we showed for the first time that the protein kinase activity of RIOK2 was enhanced; six amino acids were identified to be phosphorylated frequently in pan-cancer, among which Ser149 and Asn397 appeared to be tumor-specific phosphorylation sites." (PMID 36518977, 2022). "The N-shelf probe cg26082324 showed a pattern with reduced methylation in almost all examined malignancies relative to healthy tissues, suggesting that differential RIOK2 N-shelf site methylation may be related to carcinogenesis in pan-cancer." (PMID 36518977, 2022). "RIOK2 knockdown also led to a significant decrease in the protein synthesis in cancer cells." (PMID 36661680, 2022). "Therefore, further studies on RIOK2 and its roles in the occurrence, development, and immune microenvironment of tumors are essential to identify therapeutic cancer targets." (PMID 36518977, 2022).
cancer (continued). "In addition, the accumulation of hyperphosphorylated kinase is also linked to cancer; however, the relationship between RIOK2 phosphorylation and tumors has not been reported in the literature." (PMID 36518977, 2022). "We used gene expression profiles to construct RIOK2 PPI networks based on the STRING database and assessed their correlations with RIOK2 in a pan-cancer analysis." (PMID 36518977, 2022). "Thus, RIO kinases may play a promoting role in the progression of malignant tumours, but it should be noted that the role of RIOK2 in cancer cell migration and invasion has not been elucidated yet." (PMID 32125767, 2020).
tumor (7 papers, 2013 to 2022). "This study provides the first comprehensive report examining the association between tumor response and specific mutations in RIOK2." (PMID 36518977, 2022). "Although RIOK2 has been found to be strongly correlated with tumor survival and metastasis, the underlying molecular mechanism requires further exploration." (PMID 36518977, 2022). "RIOK1 and RIOK2 upregulation was associated with Akt activity in both GBM tumor specimens and cultured cells, and our results show that Akt signaling regulates RIO kinase protein stability, although the exact mechanism by which Akt regulates RIO kinase levels remains undetermined." (PMID 23459592, 2013). "Reduced RIOK2 expression in some tumor samples with increased promoter methylation was confirmed by statistical analysis of the correlation between DNA methylation and gene expression (Wilcoxon p-value < 0.05)." (PMID 36518977, 2022). "Despite its involvement with the onset and evolution of tumor processes, RIOK2 remains poorly understood in this context." (PMID 36518977, 2022). "A range of GBM cells and cell lines were examined to determine how RIOK1 and RIOK2 expression correlated with tumor cell genotype and phenotype." (PMID 23459592, 2013). "Statistical analysis demonstrated that RIOK2 expression was significantly correlated with EGFR status in tumor specimens, although some EGFR-negative tumors also showed RIOK2 immunoreactivity, while some EGFR-negative tumors did not." (PMID 23459592, 2013). "Xenograft specimens of GBM39, which is ΔEGFR-positive, showed RIOK2 expression in tumor cells, with cells displaying diffuse cytoplasmic and sub-surface RIOK2 localization." (PMID 23459592, 2013). "It remains unknown what role the aberrance in RIOK2 expression and function plays with immune cells in the tumor microenvironment." (PMID 36518977, 2022). "The involvement of RIOK2 as an oncogenic driver was described for a spectrum of tumor types." (PMID 36518977, 2022). "Thus, RIOK1 and RIOK2 overexpression appeared to be correlated with RTK mutation/overexpression and/or PTEN loss in GBM tumor cells." (PMID 23459592, 2013). "Therefore, it is essential to determine whether RIOK2 can be used as a predictive biomarker for a broader range of tumor types." (PMID 36518977, 2022). "ERGi-USU, a high affinity RIOK2 inhibitor, binds RIOK2 directly and induces a ribosomal stress signature, resulting in growth inhibition of ERG-positive VCaP tumor xenografts." (PMID 36518977, 2022). "The function of RIOK-3 is different from those of RIOK-1 and RIOK-2 in human cells, with RIOK-3 controlling tumor cell invasiveness, suppressing the activity of NF-κB and supporting type I-interferon production." (PMID 25477034, 2014). "The CD4+Th1/CD4+Th2 balance plays an important role in the tumor microenvironment, and our results showed that high expression of RIOK2 was negatively correlated with CD4+Th1/CD4+Th2 cells, indicating that RIOK2 is involved in Th1/Th2 regulation." (PMID 36518977, 2022). "Pten−/−; Ink4a/arf−/− murine astrocytes, which are immortalized by tumor suppressor mutations common in GBM, express little endogenous RIOK2 and are not gliomagenic in intracranial grafts assays." (PMID 23459592, 2013). "Due to the natural expression of RIOK2 and ERG in brain endothelial cells (data not shown), NSC139021 may affect the tumor vessels." (PMID 34572430, 2021).
RIOK2 also shares sentences with these, for which no sentence is quoted: breast invasive carcinoma (1 paper); cholangiocarcinoma (1); chronic kidney disease (1); clear cell renal cell carcinoma (1); colon adenocarcinoma (1); diabetes (1); diffuse large B-cell lymphoma (1); esophageal carcinoma (1); head and neck squamous cell carcinoma (1); hematological malignancies (1); hepatocellular carcinoma (1); infection (1); liver cancer (1); lung adenocarcinoma (1); lung carcinoma (1); lung squamous cell carcinoma (1); myelodysplastic syndrome (1); ovarian serous cystadenocarcinoma (1); pancreatic adenocarcinoma (1); rectum adenocarcinoma (1); schistosomiasis (1); skin cutaneous melanoma (1); thymoma (1); thyroid carcinoma (1); uterine corpus endometrial carcinoma (1).